TRADD (TNFRSF1A associated via death domain)
Description:
Adapter molecule for TNFRSF1A/TNFR1 that specifically associates with the cytoplasmic domain of activated TNFRSF1A/TNFR1 mediating its interaction with FADD. Overexpression of TRADD leads to two major TNF-induced responses, apoptosis and activation of NF-kappa-B. The nuclear form acts as a tumor suppressor by preventing ubiquitination and degradation of isoform p19ARF/ARF of CDKN2A by TRIP12: acts by interacting with TRIP12, leading to disrupt interaction between TRIP12 and isoform p19ARF/ARF of CDKN2A (By similarity).
Synonyms: Hs.89862
Tractability: Small molecule: it has a high-quality binding pocket. Antibody: its Gene Ontology location is reachable by antibodies, with high confidence. PROTAC: ubiquitination databases record sites on it; its protein half-life has been measured.
Gene: Protein-coding gene on chromosome 16 (67,153,969 to 67,163,760, reverse strand). Ensembl gene ENSG00000102871.
Subcellular location: Nucleus; Cytoplasm; Cytoplasm, cytoskeleton
Subcellular location (Human Protein Atlas): Cytosol
Pathways (Reactome):
Programmed Cell Death: CASP8 activity is inhibited; Caspase activation via Death Receptors in the presence of ligand; Dimerization of procaspase-8; RIPK1-mediated regulated necrosis; Regulation by c-FLIP; Regulation of necroptotic cell death
Signal Transduction: Regulation of TNFR1 signaling; TNF signaling; TNFR1-induced NF-kappa-B signaling pathway; TNFR1-induced proapoptotic signaling
Disease: Defective RIPK1-mediated regulated necrosis
Gene Ontology:
Molecular function: death domain binding; identical protein binding; kinase binding; protein binding; protein-macromolecule adaptor activity; transmembrane receptor protein tyrosine kinase adaptor activity; signaling adaptor activity; molecular adaptor activity
Biological process: canonical NF-kappaB signal transduction; cellular response to tumor necrosis factor; extrinsic apoptotic signaling pathway; positive regulation of canonical NF-kappaB signal transduction; positive regulation of cell migration; positive regulation of inflammatory response; positive regulation of interferon-beta production; TRAIL-activated apoptotic signaling pathway; tumor necrosis factor-mediated signaling pathway; apoptotic process; extrinsic apoptotic signaling pathway via death domain receptors; inflammatory response; intrinsic apoptotic signaling pathway in response to DNA damage; positive regulation of apoptotic process; signal transduction; cell surface receptor protein tyrosine kinase signaling pathway; positive regulation of hair follicle development; positive regulation of multicellular organismal process
Cellular component: cytoplasm; plasma membrane; receptor complex; tumor necrosis factor receptor superfamily complex; cytoplasmic side of plasma membrane; cytosol; death-inducing signaling complex; nucleus; cytoskeleton
Genetic constraint (gnomAD): Loss-of-function variants: 14 observed, 24.69 expected, observed/expected ratio (o/e) 0.57, 90% interval 0.37 to 0.89. The upper end of that interval is the gene's LOEUF score, 0.89, which puts it in group 3 of 6, group 1 being the genes least tolerant of losing a copy. Missense variants: 388 observed, 407.75 expected, observed/expected ratio (o/e) 0.95, 90% interval 0.88 to 1.03. Synonymous variants: 220 observed, 199.13 expected, observed/expected ratio (o/e) 1.1, 90% interval 0.99 to 1.24.
Homologues: Orthologues: chimpanzee TRADD (100% identical), macaque TRADD (96% identical), dog TRADD (86% identical), pig TRADD (83% identical), rabbit TRADD (82% identical), guinea pig TRADD (80% identical), rat Tradd (77% identical), mouse Tradd (77% identical), tropical clawed frog tradd (41% identical), zebrafish tradd (38% identical).
Diseases named in the same sentence as TRADD in open-access papers:
TRADD is named in the same sentence as 60 diseases in open-access papers, as found by Europe PMC text mining. Sharing a sentence is not in itself a finding about the gene and the disease. The quoted sentences say what the papers report.
breast carcinoma (8 papers, 2010 to 2022). "The involvement of TRADD in p75NTR signaling was shown to be required for NF-κB activation and control of antiapoptotic effects of neurotrophins in breast cancer cells." (PMID 28765645, 2017). "miR‐30c‐2‐3p negatively regulates NF‐кB signaling by targeting TRADD in breast cancer cells." (PMID 34631522, 2021). "A binding site next to the p75NTR DD homodimerization interface indicates that TRADD DD recruitment to p75NTR requires separation of the p75NTR DD homodimer, explaining the mechanism of NGF-dependent activation of p75NTR-TRADD-mediated antiapoptotic pathway in breast cancer cell." (PMID 28765645, 2017). "Three genes, TRADD, BNIP3L, and CASP9, increase in both cell lines with loss of Sin3A, demonstrating that Sin3A possesses some overlapping gene regulation between breast cancer cell lines, as may be expected." (PMID 20920219, 2010). "Based on these findings, we further found that the downregulation of DNA methylation of three CpG sites, TSC1 (cg14350545), FADD (cg02794589), and TRADD (cg05178604) could significantly prolong the survival of breast cancer patients (DNA methylation survival curves in the TCGA)." (PMID 33194583, 2020). "The plots showed that the survival of breast cancer patients with reduced methylation of TSC1 (cg14350545), FADD (cg02794589), and TRADD (cg05178604) was significantly improved." (PMID 33194583, 2020). "In addition, several regulatory genes in the IL-17 signaling pathway, such as TNFAIP3, TRADD, and IKBKE, were also observed to be correlated with PD-1 and/or PD-L1 in one or more cohorts of breast cancer samples." (PMID 33102239, 2020).
glioblastoma (8 papers, 2015 to 2025). The most malignant astrocytic tumor (WHO grade IV). "Upregulated expression of TRADD is sufficient to activate NF-κB in glioblastoma (GBM) cancer stem cells (GSCs)." (PMID 35330670, 2020). "Upregulated expression of TRADD activates NF-κB in glioblastoma (GBM) cancer stem cells (GSCs)." (PMID 36627897, 2022). "Consequently, we reported an increase in the transcription and expression of the DISC complex components, including TNFR1, FADD and TRADD, leading to the activation of cleaved caspase 8 and ultimately resulting in caspase-dependent cell death of glioblastoma cells." (PMID 38212807, 2024). "To further characterize gene expression in the Ad-GSCs and Sp-GSCs tumor xenografts, we examined the expression of genes previously defined to be characteristic of the Classical (FGFR3, PDFA, EGFR, AKT-2 and Nestin) and Mesenchymal (CHI3L1, TRADD, NF1, RelB and CASP4) glioblastoma subtypes." (PMID 25955030, 2015). "Moreover, high TRADD expression in glioblastoma (GBM) correlates with worse progression-free survival, indicating that TRADD may promote chemoresistance in tumor cells by activating the NF-κB pathway." (PMID 40565323, 2025).
acute myeloid leukemia (2 papers, 2023 to 2025). Acute myeloid leukemia (AML) is a group of neoplasms arising from precursor cells committed to the myeloid cell-line differentiation. "In acute myeloid leukemia (AML), low TRADD expression is associated with poor prognosis, suggesting its utility as a prognostic biomarker." (PMID 40565323, 2025). "Patients with acute myeloid leukemia who have high TRADD expression show a significantly prolonged OS similar to that of patients with LUAD75." (PMID 37864090, 2023).
acute myocardial infarction (2 papers, 2021 to 2023). Necrosis of the myocardium, as a result of interruption of the blood supply to the area. "CircROBO2 enhances the expression of TNFRSF1A-associated death domain protein (TRADD) by sponging miR-1184, which promotes apoptotic cell death and exacerbates cardiac dysfunction after myocardial infarction." (PMID 36835653, 2023).
colon cancer (2 papers, 2015 to 2022). "Otherwise, the protein expression levels of TRADD, H2AC6, VDAC3, JMJD7-PLA2G4B, TRAF2, and DAPK1 in colon cancer tissues and normal tissues in the HPA database were shown, which were consistent with the expression levels of these genes in RNA levels." (PMID 36505813, 2022). "In present study, we demonstrated that the expression of IL-32α concomitantly increased the signaling complex of TNFR1 with TRADD, TRAF2, and RIP1 in colon cancer cell, AOM-induced CRC mice, and colon cancer patient tissues." (PMID 25909160, 2015).
liver cancer (2 papers, 2022 to 2023). An epithelial or non-epithelial malignant neoplasm that arises from the liver. "Specifically, dehydrocrenatidine significantly increased the expression of extrinsic pathway components (FAS, DR5, FADD, and TRADD) as well as intrinsic pathway components (Bax and Bim L/S) in liver cancer cells." (PMID 35455398, 2022).
melanoma (2 papers, 2023 to 2024). A malignant, usually aggressive tumor composed of atypical, neoplastic melanocytes. "BCL10 (3.84-fold), TRADD (2.71-fold), CYCS (2.51-fold), DIABLO (2.43-fold), BAD (2.36-fold), BID (2.17-fold), TNFSF8 (2.13-fold), TNFSF10 (2.11-fold), BAX (2.03-fold), and FAS (2.01-fold) were also proapoptotic genes highly upregulated in response to UA treatment in A-375 melanoma cells." (PMID 39473730, 2024).
Splenomegaly (2 papers, 2014 to 2019). Abnormal increased size of the spleen. "While reducing apoptosis in the intestine, the rescue through haplosufficiency of TRADD did not lead to lymphadenopathy and splenomegaly in the resulting Ripk1−/−Ripk3−/−Tradd+/− mice, unlike the severe lpr-like symptom in Ripk3−/−Fadd−/− or Ripk1−/−Ripk3−/−Fadd−/− mice 29,33." (PMID 30741936, 2019).
viral infection (2 papers, 2015 to 2019). "The results may provide new insights into the role of fish TRADD in fish virus infection." (PMID 31620373, 2019).
Alzheimer disease (1 paper, 2021). A progressive, neurodegenerative disease characterized by loss of function and death of nerve cells in several areas of the brain leading to loss of cognitive function such as memory and language. "In the postmortem human Alzheimer’s disease hippocampus, there are increases in TRADD expression with the largest increases in patients with the highest number of neuritic plaques, whereas cortical FADD was reported to be lower in subjects with dementia and increased amyloid β pathology." (PMID 32139808, 2021).
Cognitive impairment (1 paper, 2022). Abnormal cognition is characterized by deficits in thinking, reasoning, or remembering. "HMGB1/TLR4/IL-1β/IL-1R pathway, HMGB1/TNF-α/TRADD pathway, and TRAF-2 are the key initiators of neuroinflammation for epilepsy and cognitive impairments." (PMID 35656438, 2022).
colorectal cancer (1 paper, 2024). A primary or metastatic malignant neoplasm that affects the colon or rectum. "In a TNF-α-stimulated tumour cell in the inflammatory colorectal cancer microenvironment, upon binding of TNF-α to its receptor TNFR1, adaptor proteins TRADD and TRAF2 are recruited with cIAP-1 and/or cIAP-2 and RIP kinase." (PMID 38600086, 2024).
COVID-19 (1 paper, 2023). A disease caused by infection with severe acute respiratory syndrome coronavirus 2. "The proteins encoded by the ‘dark’ genes TRADD, FOS and DDGs RELB, JUN, IKBKG are involved in the MAPK signaling pathway, which is a potential signaling pathway for the spread and development of COVID-19." (PMID 37853311, 2023).
Crohn disease (1 paper, 2022). A gastrointestinal disorder characterized by chronic inflammation involving all layers of the intestinal wall, noncaseating granulomas affecting the intestinal wall and regional lymph nodes, and transmural fibrosis. "Furthermore, A20 upregulation inhibits intestinal epithelial cell apoptosis in Crohn’s disease by affecting the functions of tumor necrosis factor receptor 1 (TNFR1), TNFR1-associated death domain protein (TRADD) and RIPK1." (PMID 35592427, 2022).
endometriosis (1 paper, 2021). The growth of functional endometrial tissue in anatomic sites outside the uterine body. "In endometriosis, TNF Alpha binds to TRADD (tumor necrosis factor receptor type 1-associated death domain protein) that activates the IKK complex and the NF-kB p50/p65 complex involved in gene transcription that regulates gene transcription for innate immunity, inflammation, and cell survival." (PMID 34194730, 2021).
fibrosarcoma (1 paper, 2020). A malignant mesenchymal fibroblastic neoplasm affecting the soft tissue and bone. "Treatment with TNF resulted in the formation of the TNF receptor signalling complex‐I (TNFR‐SC, also referred to as complex‐I) in the human fibrosarcoma cell line HT1080, as evidenced by the recruitment of bona fide TNFR‐SC components such as RIPK1, SHARPIN and TRADD (Fig EV2A)." (PMID 32419365, 2020).
head and neck carcinoma (1 paper, 2011). A carcinoma that arises from the head and neck region. "Given this cellular behavior of the head and neck carcinoma in which this particular signaling pathway is already activated, it is plausible that NSP 5a3a may be altering this signaling pathway in favor of apoptosis through use of TRAF2 and TRADD." (PMID 22170762, 2011).
hypertrophic cardiomyopathy (1 paper, 2020). A condition in which the myocardium is hypertrophied without an obvious cause. "In the same model, mice lacking the TNFR1 adaptor molecule TRADD also developed significantly attenuated fibrosis with better cardiac functions, suggesting a key role of the TNFR1–TRADD-dependent cell death in hypertrophic cardiomyopathy." (PMID 33053859, 2020).
liver disease (1 paper, 2025). "This dual regulatory mechanism enables TRADD to play a crucial role in the processes of cell death, inflammation, and fibrosis in liver diseases." (PMID 40565323, 2025). "This review systematically examines the structure and function of TRADD, as well as its critical contributions to liver disease progression, offering insights into its potential as a therapeutic target." (PMID 40565323, 2025). "In recent years, TNFR1-associated death domain protein (TRADD), a pivotal adaptor molecule in the TNF signaling pathway, has been found to play a dual regulatory role in the pathogenesis of liver diseases." (PMID 40565323, 2025). "As a key adaptor molecule in death receptor signaling, TRADD plays a pivotal role in the pathogenesis of various liver diseases—including HCC, ALD, MASLD, ALI, viral hepatitis, and liver fibrosis—by regulating apoptosis, inflammatory responses, and fibrotic progression." (PMID 40565323, 2025). "In summary, TRADD is increasingly recognized as a key player in liver disease pathogenesis." (PMID 40565323, 2025).
liver fibrosis (1 paper, 2025). "In ALD, TRADD-mediated apoptosis is closely linked to the progression of liver fibrosis." (PMID 40565323, 2025). "Notably, gallic acid (GA) has been shown to alleviate fibrosis by inducing necroptosis of activated HSCs via the TNF-α/TRADD/RIP3 pathway, offering a potential therapeutic strategy for liver fibrosis." (PMID 40565323, 2025).
malignant glioma (1 paper, 2015). A grade III or grade IV glioma arising from the central nervous system. "In established malignant glioma cells, TRADD levels were inversely correlated with miR-31 status." (PMID 26164206, 2015).
myeloid neoplasm (1 paper, 2025). Proliferation of myeloid cells originating from a primitive stem cell. "The downregulation of TRADD expression (16q22) and deletion of CBFB (16q22.1) in patients with myeloid neoplasms have been associated with poor prognosis." (PMID 40282453, 2025).
nasopharyngeal carcinoma (1 paper, 2021). A carcinoma arising from the nasopharyngeal epithelium. "Studies on nasopharyngeal carcinoma (NPC) showed LMP1 induced DNMT-1 protein and RNA expression NP69 (stably expressed LMP1), in addition to siRNA targeting of JNK, c-Jun and TRADD, LMP1-YYD domain and LMP1 observed reduced DNMT-1 expression by 20%, 40%, 60% and 50%." (PMID 33670008, 2021).
neuroblastoma (1 paper, 2023). Neuroblastoma (NB) is the most common solid, extracranial childhood tumor. "In neuroblastoma, studies have shown that genistein downregulates survival proteins (e.g., BCL2) and induces death factors and death domains (e.g., TNFR-1, TRADD, FADD)." (PMID 38249515, 2023).
peripheral T-cell lymphoma (1 paper, 2024). "The TNF receptor superfamily member 1B (TNFRSF1B), TNFRSF1A linked by the death domain TRADD, and TRAF1 associated with TNF receptors are inhibited in peripheral T-cell lymphoma when chemotherapy resistance occurs." (PMID 38468267, 2024).
prion disease (1 paper, 2024). A transmissible disease that is caused by a protein that is able to induce abnormal folding of normal cellular proteins, leading to characteristic spongiform brain changes, which are associated with neuronal loss without an inflammatory response. "Collectively, the data suggests the inhibition of TRADD expression in this mouse prion disease." (PMID 38802941, 2024). "The upregulated Fas, FasL, and RIPK1, alongside reduced TRADD levels, may account for the pronounced microgliosis observed in this prion disease mouse model." (PMID 38802941, 2024). "Conversely, the deficiency in TRADD and TRAF2 might weaken neuronal and oligodendrocyte cell survival pathways while amplifying TNFα-TNFR1-RIPK1-FADD-caspase-8 mediated cell death pathways, presenting a complex landscape of cellular fate determination in prion disease pathology." (PMID 38802941, 2024). "Similarly restoring RIPK1, TRADD and TRAF2 expression would be direct clinical implications on prion diseases." (PMID 38802941, 2024). "Interestingly, not a single study so far has focused into the crucial role of TRADD, TRAF2, FADD, and RIPK1 in prion diseases." (PMID 38802941, 2024).
Salmonella Infections (1 paper, 2020). Infections with bacteria of the genus SALMONELLA. "In this study, we show that TRADD, FADD, and RIPK1 are GlcNAcylated by NleB, TRADD is GlcNAcylated by SseK1, and TNFR1 is GlcNAcylated by SseK3 during EPEC or Salmonella infection, which are consistent with previous studies." (PMID 32432056, 2020). "One recent proteomics study have shown that TRADD and TNFR1 are the preferential substrates of SseK1 and SseK3, respectively, during Salmonella infection." (PMID 32432056, 2020). "One recent proteomics study together with our study have indicated the preferential substrate(s) is TRADD for SseK1, TNFR1 for SseK3 during Salmonella infection." (PMID 32432056, 2020).
skin inflammation (1 paper, 2014). "Here we show that the skin inflammation in Sharpincpdm/cpdm mice is triggered by TNFR1-mediated TRADD- and FADD-dependent apoptosis of keratinocytes." (PMID 25443631, 2014). "Collectively, our results show that TNFR1-induced TRADD- and FADD-dependent apoptosis of Sharpin-deficient keratinocytes triggers the chronic proliferative dermatitis phenotype in Sharpincpdm/cpdm mice." (PMID 25443631, 2014). "In addition, we provide genetic evidence that TNFR1-mediated, TRADD- and FADD-dependent apoptosis of Sharpin-deficient keratinocytes induces skin inflammation in these mice." (PMID 25443631, 2014). "Here we report the specific function of Sharpin in the regulation of apoptosis and skin inflammation, which are mediated through FADD and TRADD." (PMID 25443631, 2014). "As keratinocyte apoptosis and skin inflammation in Sharpincpdm/cpdm mice were suppressed by epidermal-specific deletion of FADD or TRADD, we sought to investigate how the lack of FADD, TRADD, and RIPK3 proteins impact on TNF-induced cell viability in Sharpin-deficient cells." (PMID 25443631, 2014).